NPM1 (nucleophosmin 1)
Diseases named in the same sentence as NPM1 in open-access papers (continued):
Sharing a sentence is not in itself a finding about the gene and the disease.
colitis (2 papers, 2024 to 2025). Inflammation of the colon. "Collectively, these findings indicated that NPM1 has a pivotal role in impeding colitis-associated colon tumorigenesis by restricting tumor development and growth." (PMID 39103576, 2024). "Npm1+/− mice were more susceptible to acute colitis and experimentally induced CAC than littermate controls." (PMID 39103576, 2024). "As expected, heterozygous overexpression of Npm1 prevented the exacerbated DSS-induced colitis caused by the Npm1 haploinsufficiency." (PMID 39103576, 2024). "The inadequate mitochondrial activation of ILC3 in the acute phase caused by heterozygous deletion of Npm1 could lead to exacerbated colitis." (PMID 39103576, 2024). "These transcriptional results indicated that the NF-κB pathway in ILC3s was activated by DSS-induced colitis and that NPM1 contributes to the regulation of a subset of NF-κB target genes." (PMID 39103576, 2024). "We also established a trinitrobenzene sulfonic acid (TNBS)-induced colitis model and evaluated the progress of colitis in WT and Npm1+/− mice." (PMID 39103576, 2024). "We also generated Npm1flox/flox mice and crossed them with Villincre/+ mice to directly assess a role in protection against colitis for NPM1 in colonic epithelial cells." (PMID 39103576, 2024). "Meanwhile, NPM1 bound to p65 and participated in downstream transcriptional regulation in ILC3s in colitis." (PMID 39103576, 2024). "Because RORc-Cre will also delete Npm1 in conventional T cells and γδT cells, we examined the function of various T cell subsets and excluded their contributions to exacerbated colitis in Rorccre/+Npm1flox/flox mice by depleting T cells using a CD3 antibody." (PMID 39103576, 2024). "Here we demonstrated that TFAM is highly expressed in ILC3s and acts as a key downstream effector of NPM1 in DSS-induced colitis." (PMID 39103576, 2024). "Immunofluorescence analysis of ILC3s revealed that p65 was localized in the cytoplasm and NPM1 was localized in the nucleus in the noninflammatory steady state, whereas p65 accumulated in the nucleus after DSS-induced colitis and colocalized with NPM1." (PMID 39103576, 2024). "In this study, we demonstrated that NPM1, a protein that is abundant in colonic ILC3s, is critical for the activation of IL-22 production in response to colitis." (PMID 39103576, 2024). "Conditional deletion of Npm1 in the ILC3 lineage exacerbated colitis and decreased protective IL-22 secretion." (PMID 39103576, 2024). "In summary, our study highlights the role of NPM1 in maintaining mitochondrial function and IL-22 production in ILC3s in the progression of colitis." (PMID 39103576, 2024). "In this study, we investigate the protective role of NPM1 in gut homeostasis and in the prevention of colitis." (PMID 39103576, 2024). "After a 7-day DSS treatment, mice receiving Npm1-haploinsufficient BM exhibited more severe colitis compared to mice receiving Npm1 WT BM cells." (PMID 39103576, 2024). "ILC3-specific deficiency of nucleophosmin 1 (NPM1) in mice did not affect the number of ILC3s but resulted in decreased IL-22 production and exacerbated colitis." (PMID 40498001, 2025). "However, in DSS-induced colitis, an elevation of these cells was observed in Npm1+/− mice compared to WT mice." (PMID 39103576, 2024). "However, only the expression of Cxcl2 and Ccl4 was markedly decreased in Npm1+/− ILC3s compared to WT ILC3s from mice with DSS-induced colitis." (PMID 39103576, 2024). "Collectively, these data indicated that NPM1 has a protective role in the mouse colitis model." (PMID 39103576, 2024). "Our subsequent investigation aimed to explain why NPM1 is downregulated in UC and whether overexpression of NPM1 could ameliorate colitis." (PMID 39103576, 2024). "The decreased production of IL-22 in ILC3s may contribute to the observed dysregulation of Reg3b and Reg3g in Npm1+/− mice in DSS-induced colitis, and thus impaired intestinal microbiota homeostasis." (PMID 39103576, 2024).
colitis (continued). "Here we identified p65 as the top interacting protein with NPM1 in ILC3s in DSS-induced colitis and observed the subcellular translocation of p65 and colocalization with NPM1 in the nucleus of ILC3s to activate downstream gene transcription after inflammatory stimulation." (PMID 39103576, 2024). "However, bezafibrate had minimal impact on mice with sufficient NPM1 function, suggesting that both NPM1 and bezafibrate maintain mitochondrial function to limit colitis." (PMID 39103576, 2024). "Additionally, Npm1+/− ILC3 exhibited similar alterations in TNBS-induced colitis." (PMID 39103576, 2024). "To specifically decipher the cell-intrinsic role of Npm1 in colonic ILC3s, we generated Rorccre/+Npm1flox/flox mice that lack Npm1 on ILC3s and subjected the mice to DSS-induced colitis." (PMID 39103576, 2024). "Mechanistically, we found that NPM1 acted as a transcription cofactor that bound p65 and stimulated mitochondrial transcription factor A (Tfam) transcription in DSS-induced colitis." (PMID 39103576, 2024). "Overexpression of Npm1 in mice enhanced ILC3 function and reduced the severity of dextran sulfate sodium-induced colitis." (PMID 39103576, 2024). "NPM1 was abundant in ILC3s and was essential for IL-22 production in response to dextran sulfate sodium (DSS)-induced colitis." (PMID 39103576, 2024). "To confirm the protective function of NPM1 in colitis, we generated Npm1UTR−/− mice that have a genetic knockout of the 3′-UTR region of Npm1 and overexpress Npm1." (PMID 39103576, 2024). "Besides, epithelial cells, macrophages and T cells in Npm1+/− mice exhibited few differences in OXPHOS compared to those in WT mice in both steady state and DSS-induced colitis conditions." (PMID 39103576, 2024). "Results indicated that the ratio of Lin−c-Kit+ (LK) cells, Lin−Sca1+c-Kit+ (LSK) cells and LSlowKlow cells in the BM of Npm1+/− mice was elevated compared with that of Npm1+/+ mice both in steady state and DSS-induced colitis conditions, which is a characteristic phenotype of MDS21,31,32." (PMID 39103576, 2024). "Mice lacking Npm1 in ILC3s exhibited decreased IL-22 production and accelerated development of colitis." (PMID 39103576, 2024). "To uncover mechanisms by which NPM1 regulates ILC3 expansion and function, we performed RNA-seq (smart-seq2) of Live+Lin−CD45lowCD90high LPLs27,40 from colon of WT and Npm1+/− mice with colitis induced by DSS treatment." (PMID 39103576, 2024). "Collectively, these data indicated that NPM1 has a critical function in maintaining mitochondria numbers and mitochondrial metabolism in ILC3s and that impairment of such metabolism represents a mechanism by which heterozygous deletion of Npm1 exacerbates DSS-induced colitis." (PMID 39103576, 2024). "Likewise, evaluation of T cells (TH17, Treg and γδT cells) coupled with comparable colitis in two genotype mice after deletion of CD3+ T cells indicated that exacerbated colitis in Npm1-haploinsufficient mice was not attributed to T cells." (PMID 39103576, 2024). "Given that Npm1 is expressed by many types of cells and decreased under pathological conditions, it is unclear whether the exacerbated colitis in Npm1+/− mice is due to defects in hematopoietic or nonhematopoietic cells, particularly colonic epithelial cells." (PMID 39103576, 2024). "Although overexpression of Npm1 did not enhance the frequency of colonic ILC3s, a higher proportion were producing IL-22, indicating that Npm1OE enhanced the defense function of ILC3s against colitis." (PMID 39103576, 2024). "Moreover, in Npm1+/− mice exposed to DSS, bezafibrate resulted in increased percentages of total colonic ILC3s, IL-22+ ILC3s and IL-22 production by ILC3s, suggesting that sufficient mitochondrial OXPHOS and biogenesis are required for ILC3 activity in DSS-induced colitis." (PMID 39103576, 2024).
colitis (continued). "Accordingly, NPM1 is crucial for the heightened demand of TFAM to subsequently increase mitochondrial function in ILC3s, not other cell types, during DSS-induced colitis." (PMID 39103576, 2024).
COVID-19 (2 papers, 2021 to 2023). A disease caused by infection with severe acute respiratory syndrome coronavirus 2. "For example, NPM1 was present in the COVID-19-associated protein–protein interaction (PPI) network module and associated with enhanced viral replication of COVID-19." (PMID 37956172, 2023).
esophageal squamous cell carcinoma (2 papers, 2022 to 2025). Esophageal squamous cell carcinoma (ESCC) is a type of esophageal carcinoma (EC) that can affect any part of the esophagus, but is usually located in the upper or middle third. "LncRNA SLC25A21-AS1, a lipid metabolism-related lncRNA, promoted the esophageal squamous cell carcinoma (ESCC) cells’ migration and proliferation via the SLC25A21/NPM-1/c-Myc axis." (PMID 40868150, 2025).
essential thrombocythemia (2 papers, 2021 to 2023). A chronic myeloproliferative neoplasm that involves primarily the megakaryocytic lineage. "Molecular diagnosis of MPN occurs from the presence of mutant JAK2-V617F and associated diseases include essential thrombocythemia (ET) and myelofibrosis (MF) of which NPM1-mutations have been found on a rare occasion." (PMID 36834572, 2023).
fungal infections (2 papers, 2011 to 2023). "Vitamin C/D supplementation significantly improved overall survival of NPM1-mutant AML patients and reduced the incidence of bacterial or fungal infections." (PMID 37958646, 2023).
latent infection (2 papers, 2012 to 2023). "Most importantly, the robust impairments of cell growth caused by NPM1 knockdown in IB4 LCL emphasize the conspicuous biological role of NPM1 in EBV latent infection." (PMID 23271972, 2012). "Furthermore, we have shown that oligomerized NPM1 is charged by ATP and binds to EBNA2, which is crucial for its ability to stabilize its interaction with the DNA binding protein RBP-Jκ, which is in turn essential for supporting the transcriptional cascades of EBV latent infection." (PMID 23271972, 2012).
neutropenia (2 papers, 2025 to 2026). A decrease in the number of neutrophils found in the blood. "In MDS mouse models, genetic ablation of Fbxo11 exacerbated neutropenia concomitant with a profound decrease in NPM1 protein levels." (PMID 41542766, 2026). "Moreover, in the Nup98-Hoxd13 model, the neutropenia and monocytopenia in Fbxo11-knockdown animals were even worse and were accompanied by striking BM hypercellularity and a reduction in NPM1 protein levels." (PMID 41542766, 2026).
oral cancer (2 papers, 2023 to 2024). "For instance, acetylated NPM1 has been reported to transcriptionally regulate certain genes associated with oral cancer and to localize at their promoters." (PMID 38243170, 2024). "More specifically, NPM1 has multiple functions involving nucleolus organization and function and has been identified as overexpressed in clinical studies of gene dysregulation among oral cancers." (PMID 36674758, 2023).
prostate adenocarcinoma (2 papers, 2014 to 2025). "In prostate adenocarcinoma, higher expression of NPM1 was observed in Gleason 4 pattern specimens compared to Gleason 3 pattern specimens." (PMID 40705480, 2025). "The mRNA expression of NPM1 and FBL was increased in PCa specimens compared to normal prostatic tissues in the prostate adenocarcinoma [The Cancer Genome Atlas (TCGA)] dataset accessed through UALCAN (The University of ALabama at Birmingham CANcer data analysis Portal)." (PMID 40705480, 2025).
rectal adenocarcinoma (2 papers, 2024 to 2026). "Analysis of The Cancer Genome Atlas database revealed that lower NPM1 mRNA correlated with worse overall survival in patients with either COAD or rectum adenocarcinoma (READ)." (PMID 39103576, 2024).
retinoblastoma (2 papers, 2012 to 2014). A malignant tumor that originates in the nuclear layer of the retina.
abortion (1 paper, 2024). the ending of pregnancy by removing a fetus or embryo before it can survive outside the uterus.
Anxiety (1 paper, 2025). Intense feelings of nervousness, tension, or panic often arise in response to interpersonal stresses. "Interestingly, we identified 13 overlapping genes regulated in the overexpression experiment and only three genes regulated in the lbx1a(−/−) mutant line (NPM1, PCLO, and FADS2), which are candidate genes from anxiety GWAS studies." (PMID 41440000, 2025).
atherosclerosis (1 paper, 2023). A disease characterized by the build-up of fatty material and calcium deposition in the arterial wall resulting in partial or complete occlusion of the arterial lumen. "Several proteins downregulated in eWAT, such as PADI2, PSAP, NCK1, and NPM1, with proven pro-inflammatory properties that are normally secreted into the extracellular space, have been linked to the progression of atherosclerosis." (PMID 38017481, 2023).
benign prostatic hyperplasia (1 paper, 2022). A non-cancerous nodular enlargement of the prostate gland. "The higher level of anti-NPM1 antibody in PCa compared to the one detected in benign prostatic hyperplasia (BPH) patients and healthy individuals." (PMID 36303548, 2022).
blood disease (1 paper, 2022). A disease that occurs in the blood. "Currently, NPM1 research is focused more on cancer than blood diseases." (PMID 36188614, 2022).
brain tumor (1 paper, 2020).
cataract (1 paper, 2024). Partial or complete opacity of the crystalline lens of one or both eyes that decreases visual acuity and eventually results in blindness. "Our findings provide new insights into the pathogenesis of cataracts and point to potential paths for intervention, underscoring the importance of NPM1 in the cellular processes of cataract formation." (PMID 38662949, 2024). "Nevertheless, the role of NPM1 in ocular diseases, particularly cataracts, remains largely uncharted." (PMID 38662949, 2024). "Our bioinformatics research revealed that NPM1 is elevated in cataract samples, implying that it plays a role in cataract pathogenesis." (PMID 38662949, 2024). "Our study discovered seven aging-related genes, including NPM1, that had substantial relationships with cataracts." (PMID 38662949, 2024). "The GSE101727 dataset was retrieved for this research, and via extensive bioinformatics analysis, the key aging-related gene in the etiology of cataracts, NPM1, was identified." (PMID 38662949, 2024). "Based on this, it was speculated that PDGFRB and CDKN1A were promoting genes, and PTEN, CANX, COL4A2, EIF2S1, and NPM1 were suppressing genes in cataract pathogenesis." (PMID 38662949, 2024). "However, there is no research related to NPM1 and cataracts yet." (PMID 38662949, 2024).
congestive heart failure (1 paper, 2021). Failure of the heart to pump a sufficient amount of blood to meet the needs of the body tissues, resulting in tissue congestion and edema. "This study follows the previous report of one NPM1-mutated AML patient unfit for intensive CHT due to congestive heart failure, who was successfully treated with single-agent dactinomycin at the dose of 12.5 μg/Kg/day for 5 days." (PMID 33654209, 2021).
diabetes (1 paper, 2024). "The coefficients for each parameter were as follows: 0.4029 for abnormal NT-pro BNP, 0.1706 for history of diabetes, 0.6376 for NPM1, 0.0294 for FLT3, 0.0383 for Ras, 0.1220 for WT1, 0.5206 for JAK2, 0.0055 for WBC, 0.0942 for RBC, and − 0.0007 for EF." (PMID 38273254, 2024).
endometrial adenocarcinoma (1 paper, 2014). "Expression of NPM1 was up-regulated by estrogen in primary-cultured human endometrial adenocarcinoma cells." (PMID 25663821, 2014). "And the ERα expression as a result of E2 treatment in primary-cultured FIGO stages I endometrial adenocarcinoma cells exhibited a similar tendency to that of NPM1." (PMID 25663821, 2014). "The association between NPM1 expression and estrogen and estrogen receptor signaling was investigated in primary-cultured FIGO stage I endometrial adenocarcinoma cells." (PMID 25663821, 2014). "Addition of estrogen receptor-α antagonist ICI 182780 attenuated E2-induced mRNA and protein expression of NPM1 in the primary-cultured FIGO stages I endometrial adenocarcinoma cells." (PMID 25663821, 2014). "So we investigated whether the estrogen-regulated NPM1 expression was correlated with estrogen receptor-α in the primary-cultured FIGO stages I human endometrial adenocarcinoma cells." (PMID 25663821, 2014). "To investigate if there is a possible hormonal regulation of NPM1 expression, we quantified NPM1 expression levels in primary-cultured FIGO stages I endometrial adenocarcinoma cells stimulated with estrogen (E2 0, 0.1, 0.5, 1, 5 μm/ml) for 24 h using qRT-PCR and Western blotting." (PMID 25663821, 2014).
endometrioid adenocarcinoma (1 paper, 2014). An adenocarcinoma characterized by the presence of malignant glandular epithelial cells resembling endometrial cells. "Overexpression of NPM1 may play a role in the effects of estrogen on the malignant progression of endometrioid adenocarcinoma via ERα signaling." (PMID 25663821, 2014). "Overexpression of NPM1 may play a role via ERα in the effects of estrogen on the malignant progression of endometrioid adenocarcinoma, which may extend our understanding of the oncogenesis of steroid hormone-related cancers and have significance for the therapy of this carcinoma." (PMID 25663821, 2014).
enteritis (1 paper, 2024). Inflammation of the small intestine. "Without development defects, heterozygous deletion of Npm1 in ILC3 also contributed to exacerbated enteritis and reduction of ILC3, which appears to be in a dose-dependent manner." (PMID 39103576, 2024). "Furthermore, clearance of CD11b+ myeloid cells failed to rescue the exacerbated enteritis in Npm1+/− mice, suggesting that NPM1 in myeloid cells was insufficient to regulate intestinal inflammation." (PMID 39103576, 2024).
eosinophilia (1 paper, 2025). "In that case, an NPM1 mutation was identified at AML diagnosis and, retrospectively, also at the initial presentation of eosinophilia." (PMID 40567444, 2025).
erythroleukemia (1 paper, 2024). Acute erythroid leukemia characterised by the presence of at least 50% erythroid precursors and at least 20% myeloblasts in the bone marrow.
esophageal carcinoma (1 paper, 2022). A primary or metastatic malignant neoplasm involving the esophagus. "At the same time, the expression difference of NPM1 between esophageal carcinoma (ESCA) samples and control samples was verified by in vitro experiments." (PMID 36188614, 2022).
gastric tumors (1 paper, 2014). "Although the expression of NPM1 is heterogeneous in gastric tumors, our results suggest that NPM1 down-regulation may have a role in gastric carcinogenesis and may help in the selection of anticancer treatment strategies." (PMID 24410879, 2014). "NPM1 protein expression was determined by Western blot in 17 pairs of gastric tumors and corresponding non-neoplastic gastric tissue." (PMID 24410879, 2014). "Here, we evaluated NPM1 gene and protein expression in gastric tumors and in corresponding non-neoplastic gastric samples." (PMID 24410879, 2014).